ALOX15 (arachidonate 15-lipoxygenase)
Description:
Non-heme iron-containing dioxygenase that catalyzes the stereo-specific peroxidation of free and esterified polyunsaturated fatty acids generating a spectrum of bioactive lipid mediators. It inserts peroxyl groups at C12 or C15 of arachidonate ((5Z,8Z,11Z,14Z)-eicosatetraenoate) producing both 12-hydroperoxyeicosatetraenoate/12-HPETE and 15-hydroperoxyeicosatetraenoate/15-HPETE. It may then act on 12-HPETE to produce hepoxilins, which may show pro-inflammatory properties (By similarity). Can also peroxidize linoleate ((9Z,12Z)-octadecadienoate) to 13-hydroperoxyoctadecadienoate/13-HPODE. May participate in the sequential oxidations of DHA ((4Z,7Z,10Z,13Z,16Z,19Z)-docosahexaenoate) to generate specialized pro-resolving mediators (SPMs)like resolvin D5 ((7S,17S)-diHPDHA) and (7S,14S)-diHPDHA, that actively down-regulate the immune response and have anti-aggregation properties with platelets. Can convert epoxy fatty acids to hydroperoxy-epoxides derivatives followed by an intramolecular nucleophilic substitution leading to the formation of monocyclic endoperoxides. Plays an important role during the maintenance of self-tolerance by peroxidizing membrane-bound phosphatidylethanolamine which can then signal the sorting process for clearance of apoptotic cells during inflammation and prevent an autoimmune response. In addition to its role in the immune and inflammatory responses, this enzyme may play a role in epithelial wound healing in the cornea through production of lipoxin A4 (LXA(4)) and docosahexaenoic acid-derived neuroprotectin D1 (NPD1; 10R,17S-HDHA), both lipid autacoids exhibit anti-inflammatory and neuroprotective properties. Furthermore, it may regulate actin polymerization which is crucial for several biological processes such as the phagocytosis of apoptotic cells. It is also implicated in the generation of endogenous ligands for peroxisome proliferator activated receptor (PPAR-gamma), hence modulating macrophage development and function. It may also exert a negative effect on skeletal development by regulating bone mass through this pathway. As well as participates in ER stress and downstream inflammation in adipocytes, pancreatic islets, and liver (By similarity). Finally, it is also involved in the cellular response to IL13/interleukin-13.
Synonyms: 12-LOX; 15-LOX; 15-LOX-1; LOG15
Tractability: Small molecule: a high-quality ligand is known; it belongs to a druggable protein family. Antibody: UniProt places it where antibodies can reach, with high confidence; its Gene Ontology location is reachable by antibodies, with medium confidence. PROTAC: ubiquitination databases record sites on it; a small molecule that binds it is known.
Target class: Enzyme; Oxidoreductase
Chemical probes: CHEMBL3604174, ML094, ML351
Gene: Protein-coding gene on chromosome 17 (4,630,919 to 4,642,294, reverse strand). Ensembl gene ENSG00000161905.
Subcellular location: Cytoplasm, cytosol; Cell membrane; Lipid droplet
Pathways (Reactome):
Metabolism: Biosynthesis of DHA-derived SPMs; Biosynthesis of DPAn-3-derived protectins and resolvins; Biosynthesis of DPAn-6 SPMs; Biosynthesis of E-series 18(R)-resolvins; Biosynthesis of E-series 18(S)-resolvins; Biosynthesis of protectins; Synthesis of 12-eicosatetraenoic acid derivatives; Synthesis of 15-eicosatetraenoic acid derivatives; Synthesis of Leukotrienes (LT) and Eoxins (EX)
Immune System: Interleukin-4 and Interleukin-13 signaling
Gene Ontology:
Molecular function: arachidonate 12(S)-lipoxygenase activity; arachidonate 15-lipoxygenase activity; linoleate 13S-lipoxygenase activity; phosphatidylinositol-4,5-bisphosphate binding; protein binding; iron ion binding; hydroperoxy icosatetraenoate dehydratase activity; hydroperoxy icosatetraenoate isomerase activity; metal ion binding; oxidoreductase activity, acting on single donors with incorporation of molecular oxygen, incorporation of two atoms of oxygen
Biological process: arachidonate metabolic process; cellular response to calcium ion; cellular response to interleukin-13; linoleic acid metabolic process; lipid metabolic process; lipoxygenase pathway; positive regulation of cell-substrate adhesion; positive regulation of ERK1 and ERK2 cascade; regulation of inflammatory response; apoptotic cell clearance; bone mineralization; fatty acid oxidation; hepoxilin biosynthetic process; inflammatory response; lipoxin A4 biosynthetic process; long-chain fatty acid biosynthetic process; negative regulation of adaptive immune response; ossification; phosphatidylethanolamine biosynthetic process; positive regulation of actin filament polymerization; regulation of engulfment of apoptotic cell; regulation of peroxisome proliferator activated receptor signaling pathway; response to endoplasmic reticulum stress; wound healing; lipid oxidation; and 1 more
Cellular component: cytoplasmic side of plasma membrane; cytosol; lipid droplet; membrane; plasma membrane; cytoplasm
Genetic constraint (gnomAD): Loss-of-function variants: 66 observed, 72.53 expected, observed/expected ratio (o/e) 0.91, 90% interval 0.75 to 1.12. The upper end of that interval is the gene's LOEUF score, 1.12, which puts it in group 4 of 6, group 1 being the genes least tolerant of losing a copy. Missense variants: 776 observed, 817.06 expected, observed/expected ratio (o/e) 0.95, 90% interval 0.89 to 1.01. Synonymous variants: 330 observed, 335.99 expected, observed/expected ratio (o/e) 0.98, 90% interval 0.9 to 1.08.
Homologues: Orthologues: chimpanzee ALOX15 (99% identical), macaque ALOX15 (95% identical), pig ALOX15 (86% identical), dog ALOX15 (84% identical), rabbit ALOX15 (79% identical), mouse Alox15 (73% identical), rat Alox15 (71% identical), tropical clawed frog alox15b (37% identical), tropical clawed frog alox12b (37% identical). Paralogues in human: ALOX12 (65% identical), ALOX5 (39% identical), ALOX15B (38% identical), ALOXE3 (38% identical), ALOX12B (35% identical).
Diseases named in the same sentence as ALOX15 in open-access papers:
ALOX15 is named in the same sentence as 178 diseases in open-access papers, as found by Europe PMC text mining. Sharing a sentence is not in itself a finding about the gene and the disease. The quoted sentences say what the papers report.
asthma (48 papers, 2011 to 2026). "ALOX15 and its metabolites are implicated in the pathophysiology of multiple inflammatory diseases, such as sepsis, arthritis, asthma, cystic fibrosis, and atherosclerosis." (PMID 36823620, 2023). "Additionally, ALOX15-induced lipid peroxidation has been shown to increase the susceptibility of asthma epithelial cells to ferroptosis." (PMID 40110046, 2025). "Additionally, one study found that haplotypic genetic variation at the locus for ALOX15 is associated with asthma." (PMID 37275375, 2023). "ALOX15 has both anti-inflammatory and inflammatory effects depending on its regulation and has been previously implicated in the development of inflammatory diseases, including asthma." (PMID 37275375, 2023). "Given the central role of pro-ferroptotic lipid metabolism in this asthma subtype, targeting arachidonate 15-lipoxygenase (ALOX15)—which is highly expressed in neutrophilic infiltrates—has emerged as a rational therapeutic strategy." (PMID 41573584, 2025). "Multiple intermediates of leukotriene metabolism (LT4AH, ALOX15), relevant in pathogenesis of airway disease and known to be EV associated, were found to be decreased in BW EVs from patients with COPD and asthma." (PMID 40553562, 2025). "Neutrophils, central to steroid-resistant asthma, promote ferroptosis partly through arachidonate 15-lipoxygenase (ALOX15), catalyzing the oxidation of membrane-bound arachidonic acid into lipid peroxides." (PMID 41573584, 2025). "Chicoric acid (CA, Compound 41), an immunologically active constituent extracted from chicory and Echinacea purpurea, alleviates asthma progression by inhibiting the key ferroptosis regulator ALOX15." (PMID 41471274, 2025). "ALOX15 can reportedly play a key role in the pathogenesis of many diseases including asthma, allergic rhinitis, and cancers of the head and neck." (PMID 40535747, 2025). "Chelidonium majus relieved OVA-induced asthma in rats by regulating the Alox15, P4ha1, Pla2g16, Pde3a, Nme1, Entpd8 and Adcy9 genes expression to restore the disorders in energy metabolism and inflammation." (PMID 38671520, 2024). "α-Glucosidase inhibitors have been used to treat T2DM, and arachidonic acid 15-lipoxygenase (ALOX15) inhibitors have been suggested to be used as treatments for asthma and T2DM." (PMID 38523640, 2024). "In a recent review, it was mentioned that human arachidonic acid 15-lipoxygenase (ALOX15) inhibitors have the potential to be used as treatments for airway inflammatory diseases, including asthma." (PMID 38523640, 2024). "Results suggest that both expression levels and covariances of ADORA3, ALOX15, and IDO1 are associated with asthma control." (PMID 37275375, 2023). "In applications to ABRIDGE and CAMP cohorts, we find evidence of both differential co-expression and differential expression across ACT scores for ADORA3, ALOX15, and IDO1, all genes which have been previously implicated in asthma." (PMID 37275375, 2023). "Regarding 12/15-LOX, Alox15−/− mice subjected to the OVA asthma model have generally demonstrated less severe asthma as measured by lung cellularity." (PMID 37253655, 2023). "Among our genes that were driven by rare variants, i.e., ALOX15, CSF2RB, IL17RA, IL33, JAK2, S1PR4, and SH2B3, previous studies supported a rare variant association between IL33, which is a known asthma locus, and eosinophil count." (PMID 35935937, 2022). "ALOX15 (genetic loci: 17p13.2) and POSTN (genetic loci: 13q13.3) genes were hypomethylated in the nasal epithelium and associated with asthma." (PMID 34566492, 2021). "ALOX15 promotes eosinophilic inflammatory diseases, such as asthma, and aspirin exacerbated respiratory disease (AERD)." (PMID 34566492, 2021). "Several studies have demonstrated increased levels of ALOX15 and its metabolites in asthma, which can lead to bronchial epithelial injury and remodeling and regulate goblet cell differentiation in asthmatic human airway epithelial cells." (PMID 32973910, 2020).
asthma (continued). "Then, ECRSwNP patients were more likely to have asthma (P = 0.003), allergic rhinitis (P = 0.044) and atopy (P = 0.034), as well as higher ALOX15 mRNA levels in nasal polyp tissues (P < 0.001)." (PMID 32973910, 2020). "They re-analyzed genes in the AA pathway, and a new SNP of ALOX15 and PTGS-1 were found to be associated with AERD risk in comparison with asthma and healthy subjects." (PMID 30254660, 2018). "Several lines of evidence indicate that ALOX15 activation in the respiratory tract contributes to asthma progression." (PMID 24465480, 2014). "In several studies, ALOX15 has been suggested to contribute to asthma pathogenesis and increased expression of epithelial ALOX15 associates with increased disease severity." (PMID 24465480, 2014). "Research utilizing gene knockout and transgenic animal models further indicates that ALOX15 contributes to the pathogenesis of various inflammation-related diseases, including neuroinflammation, atherosclerosis, asthma, rheumatoid arthritis, and metabolic inflammatory diseases." (PMID 42004954, 2026). "It has been hypothesized that ALOX15 inhibitors have the potential to be used as treatments for airway inflammatory diseases, including asthma." (PMID 38523640, 2024). "Thus, lower AHR in Alox15−/− mice correlated with decreased levels of specific myeloid and lymphoid cells with recognized roles in asthma severity." (PMID 37253655, 2023). "Thus, according to the concept of “one airway, one disease”, patients with both ECRSwNP and asthma with increased ALOX15 expression in polyp tissues, would likely benefit from treatment for both diseases." (PMID 32973910, 2020). "ALOX15 has been suggested to promote eosinophil infiltration in eosinophilic inflammatory diseases, such as aspirin-exacerbated respiratory disease, eosinophilic esophagitis, and asthma." (PMID 32973910, 2020). "Moreover, only a preliminary inference has been made that ALOX15 might play a role in the upper and lower airways involving ECRSwNP and asthma." (PMID 32973910, 2020). "We also identified three highly upregulated proteins (with fold changes of over 25), FCGBP, ALOX15, and SERPINB2, which play critical roles in human allergy, immune responses, and asthma." (PMID 38732251, 2024). "An increasing line of evidence suggests the involvement of ALOX15, including its metabolite 15-hydroxyeicosatetraenoic acid (15-HETE), in GCM and mucus hyperproduction in pathologic conditions such as asthma." (PMID 37978392, 2023). "For examples, significant DEGs in our list are involved biomarkers of Th2 response (POSTN), inflammation (NOS2, ALOX15) and mucus production (MUC5AC) corroborated with a previous metanalysis of airway gene expression in asthma." (PMID 32900903, 2020). "Compounds or extracts that inhibit both ALOX15 and α-glucosidase might be possible new sources of treatments for T2DM and asthma, especially for women." (PMID 38523640, 2024). "Notably, PSES hypomethylate ALOX15, CAPN14, and POSTN asthma genes which increases the prevalence of asthma symptoms." (PMID 36960908, 2023).
atherosclerosis (28 papers, 2008 to 2026). A disease characterized by the build-up of fatty material and calcium deposition in the arterial wall resulting in partial or complete occlusion of the arterial lumen. "By performing partial carotid ligation in ApoE−/− and ApoE−/−/ALOX15−/− mice, we showed that atherosclerosis under disturbed flow was attenuated by 12/15-LOX deficiency." (PMID 40660143, 2025). "ALOX15 catalyzed oxygenation of LDLs renders this lipid transport particle atherogenic and thus ALOX15 has been implicated in the pathogenesis of atherosclerosis." (PMID 40044044, 2025). "The enzyme 12/15-lipoxygenase (12/15-LOX, encoded by ALOX15) has emerged as a promising therapeutic target for atherosclerosis." (PMID 40660143, 2025). "Alox15, which is a lipid-peroxidizing enzyme, has been implicated in the pathogenesis of atherosclerosis, diabetes, and neurodegenerative disease." (PMID 36672863, 2023). "Human 12-lipoxygenase (encoded by ALOX12) and 15-lipoxygenase (encoded by ALOX15) have been localized to atherosclerotic plaques, suggesting that 12/15LO activity is involved in the development of atherosclerosis." (PMID 20592751, 2010). "On the other hand, Alox15−/− mice were protected from aortic lipid deposition in two mouse atherosclerosis models and these data suggest a pro-inflammatory function of the enzyme." (PMID 40653455, 2025). "We demonstrated that baicalein reversed disturbed flow-induced endothelial dysfunction and the progression of atherosclerosis, with a similar trend as observed in ALOX15 knockout mice." (PMID 40660143, 2025). "This conclusion was supported by in vivo atherosclerosis studies, in which human ALOX15 was overexpressed in mouse endothelial cells." (PMID 40653455, 2025). "We are currently exploring the impact of the Leu353Phe exchange in the Alox15 gene in a mouse atherosclerosis model but it would also be worth to test these mice in different mouse cancer models and/or in mouse models of human neurodegeneration." (PMID 40653455, 2025). "ALOX15 is involved in chronic diseases, such as atherosclerosis, and its deletion in animal disease models improves these diseases." (PMID 33595729, 2021). "Given the already known role of Alox15 in atherosclerosis, our findings underscore the central role that eoxPL and Alox isoforms play in several related forms of vascular inflammation." (PMID 30944221, 2019). "In an animal model of atherosclerosis, Alox15/Ldl receptor double knockout mice fed a PUFA-enriched diet had reduced plasma cholesterol and triglyceride levels, liver lipid levels, and aortic atherosclerosis compared to Ldl receptor knockout mice." (PMID 31333453, 2019). "The ALOX12, ALOX15, ALOX5, and ALOX5AP genes represent strong candidates for atherosclerosis risk, especially in the context of type 2 diabetes." (PMID 20592751, 2010). "Moreover, macrophage specific overexpression of human ALOX15 reduced aortic lipid deposition in a mouse atherosclerosis model, which was paralleled by increased levels of specialized pro-resolving mediators in the atherosclerotic lesions." (PMID 40653455, 2025). "ALOX15 activation is involved in the pathogenesis of atherosclerosis, hypertension, and diabetes." (PMID 27594770, 2016). "In vascular tissues of patients with atherosclerosis, DNA methylation alterations of 15-lipoxygenase (ALOX15), estrogen receptors (ESR1 and ESR2), monocarboxylate transporter 3 (MCT3), and tissue factor pathway inhibitor 2 (TFPI2) genes have been reported using a candidate gene approach." (PMID 25856389, 2015). "Whether the effect of vimentin on ALOX15 promoter activity has an impact on atherosclerosis remain to be determined." (PMID 22879973, 2012). "Further studies will determine whether a new role of vimentin in ALOX15 regulation and the sequence variation at rs2255888 in the ALOX15 is relevant to ALOX15 implication in the pathogenesis of atherosclerosis." (PMID 22879973, 2012).
atherosclerosis (continued). "We hypothesize that polymorphisms in ALOX12, ALOX15, ALOX5, and ALOX5AP genes are associated with subclinical atherosclerosis in multiple vascular beds." (PMID 20592751, 2010). "Secondly, arachidonate 15-lipoxygenase which is expressed at high levels in eosinophils may be involved in oxidative modification of LDL cholesterol and therefore in atherosclerosis, a major cause for MI." (PMID 18949100, 2008). "Transgenic mice, which express the AA 15-lipoxygenating human ALOX15 under the control of the lysozyme promoter (macrophage specific expression) in addition to the endogenous AA 12-lipoxygenating mouse Alox15, are protected from arterial lipid deposition in a mouse atherosclerosis model." (PMID 40044044, 2025). "The role of ALOX15 and ALOX15B in atherogenesis is complex due in part to the fact that atherosclerosis is a multifactorial disease entailing a complex interplay of modified lipoproteins, monocyte-derived macrophages, T cells, and the arterial wall." (PMID 31333453, 2019). "Although these results support the notion that ALOX15 can directly contribute to atherosclerosis via LDL oxidation, subsequent studies performed in transgenic animal models reported both pro-atherogenic and anti-atherogenic roles for ALOX15." (PMID 31333453, 2019). "Previous studies of vascular tissue samples revealed alterations in methylation of ALOX15, ESR1, ESR2, MCT3 and TFPI2 genes in patients with atherosclerosis." (PMID 25856389, 2015). "On account of minor human ALOX15 mRNA that were detected in atherosclerotic lesions, ALOX15 may play a role in the initiation of atherosclerosis but not in later stages of atherogenesis." (PMID 27594770, 2016). "Human arachidonate 15-lipoxygenase, a non-heme iron dioxygenase highly expressed in macrophages, has been shown to participate in these processes, but its precise role in atherosclerosis is controversial." (PMID 22879973, 2012).